EGFR (epidermal growth factor receptor)
Diseases named in the same sentence as EGFR in open-access papers (continued):
Sharing a sentence is not in itself a finding about the gene and the disease.
breast carcinoma (continued). "In addition, RTKs regulate E1A through NFI-C and NFI-X inhibition and AXL expression and thus sensitize breast cancer cells to EGFR–tyrosine kinase inhibitor chemotherapy." (PMID 37433225, 2023). "Another trial observed expression of EGFR in 88.5% of breast cancers." (PMID 36766486, 2023). "In addition to TNBC cell lines, we used the ER + breast cancer cell line T47D as the nuclear localization of EGFR is a mechanism of therapeutic resistance amongst ER + breast cancer." (PMID 36253541, 2023). "EGFR protein expression of commonly used breast cancer cell lines have been studied." (PMID 38090376, 2023). "Thus, PRL factors as well as EGFR signaling pathways interact in breast cancer development and progression." (PMID 37415164, 2023). "Liposomal encapsulation of doxorubicin and targeted delivery of the compound to EGFR overexpressing breast cancer cells was hypothesized to improve efficacy while at the same time causing less safety signals in comparison to free and untargeted application." (PMID 36879012, 2023). "However, the mechanism that induces CCL2 expression in breast cancer with EGFR and HER2 co-expression remains to be further explored." (PMID 36674955, 2023). "PTPN3 was also reported in breast cancer by dephosphorylating the epidermal growth factor receptor (EGFR), increasing sensitivity to tyrosine kinase inhibitors, and by regulation of the vitamin D receptor expression and stability, which stimulates breast cancer growth." (PMID 37200868, 2023). "EGFR signaling was responsible for cell growth, invasion, and metastasis in breast cancer." (PMID 37404768, 2023). "Furthermore, we identified a compound S62 as a small molecule disruptor of PELI1/EGFR that effectively repressed breast cancer metastasis." (PMID 36841821, 2023). "Furthermore, the combined activation of the MAPK and PI3K/AKT pathways decreased the sensitivity of breast cancer cells to a variety of targeted therapies, including the EGFR, PI3K, Akt and mTOR inhibitors." (PMID 37476189, 2023). "IL-17E was reported to induce EGFR activation in breast cancer cells." (PMID 37444399, 2023). "Interestingly, SHP-1 has also been reported to act as a tumor suppressor in breast cancer, and its expression is negatively correlated with EGFR (Epidermal growth factor receptor), which is highly expressed in 15–45% of breast cancer." (PMID 36768478, 2023). "EVs may also be fused with liposomes to create a hybrid delivery vehicle and engineered to express anti-EGFR antibodies so that they effectively target breast cancer cells." (PMID 37894887, 2023). "Consequently, disrupting the RAB27A-mediated EGFR in breast cancer attenuates the metastatic niche, leading to impaired tumor distant metastasis." (PMID 37685910, 2023). "Additionally, TFAP2C directly interacts with the EGFR gene to promote its expression, resulting in luminal breast cancer cell proliferation and an improved therapeutic effect of TKIs (Vandetanib)." (PMID 37291585, 2023). "Here, we found that PELI1 is positively correlated with EGFR in breast cancers." (PMID 36841821, 2023). "In addition, although HER2 status was important for the breast cancer treatment, other ErbB receptors (including EGFR, HER3 and HER4) were also considered to play a crucial role in breast cancer pathogenesis." (PMID 37099044, 2023). "Similarly, miR-218 was expressed highest in low-grade tumors (histologic grade 1 or 2), while EGFR was primarily expressed in high-grade breast cancer samples (histologic grade 3)." (PMID 37088795, 2023). "In breast cancer, EGFR seems to be involved in the pathogenesis and progression." (PMID 38974258, 2023).
breast carcinoma (continued). "The target tumor cells used were breast cancer cells that expressed EGFR." (PMID 37349810, 2023). "In breast cancer cells, caffeic acid prevents the phosphorylation of EGFR." (PMID 36768973, 2023). "PTK6 can promote the tumorigenesis of breast cancer by interacting with the EGFR pathway." (PMID 36690663, 2023). "Activation of the ERBB/HER family of proteins has been repeatedly implicated in oncogenesis and can be induced by various molecular alterations, including EGFR point mutations or short insertions or deletions (indels) in NSCLC and ERBB2 amplification in breast cancer." (PMID 37168365, 2023). "PELI1 physically interacted with EGFR to cooperate to promote breast cancer metastasis." (PMID 36841821, 2023). "Therefore, the usage of dual EGFR/HER2 inhibitors/modulators in breast cancer treatment is an approach worth considering." (PMID 36297358, 2022). "Other cancers may be more sensitive to SHIP2 inhibition, as SHIP2 expression is increased in breast cancer and promotes survival signals from epidermal growth factor receptor (EGF-R) in these tumors." (PMID 36500543, 2022). "Anti-human EGFR IgG1 monoclonal antibody was applied to 64Cu-DOTA-MS2 VLP to actively target EGFR-overexpressing HCC1954 breast cancer; p-aminophenylalanine (paF) unnatural amino acid was introduced at position 19 of the MS2 capsid proteins, followed by reacting with aminophenol-antibody conjugates." (PMID 36714624, 2022). "The goals of this study were to identify transcriptomic changes that arise in basal-like breast cancer cells during the development of resistance to epidermal growth factor receptor inhibitors (EGFRi) and to identify drugs that are cytotoxic once EGFRi resistance occurs." (PMID 36482068, 2022). "Here, in the present study, we identified the regulation of the FoxO signaling pathway via the modulation of four genes i.e. MDM2, STAT3, IGF1R, and GRM1 which could support the functioning of the PI3K-Akt and EGFR signal against breast cancer pathogenesis." (PMID 36686654, 2022). "According to hormone and epidermal growth factor receptor expression status, breast cancer can be divided into several molecular subtypes: triple‐negative breast cancer (TNBC), luminal A (LA), luminal B (LB), human epidermal growth factor receptor 2 (HER2) enriched, normal‐like, and so forth." (PMID 35756163, 2022). "Hence, we advocate for the use of EGFR inhibitors at the pre-metastatic stage of breast cancer subtypes with the worst prognosis instead of its use at the metastatic stage." (PMID 36380366, 2022). "The epidermal growth factor receptor (EGFR) is a surface marker of breast cancer." (PMID 35153781, 2022). "Collectively, our findings provide novel information on the mechanisms mediated by the EGFR in the tumor microenvironment that might be involved in breast cancer progression." (PMID 35406622, 2022). "Collectively, our data suggested that the EGFR signaling regulates in MSCs the expression of miRNAs that might be involved in breast cancer progression, providing novel information on the mechanisms that regulate the MSC-tumor cell cross-talk." (PMID 35406622, 2022). "Additionally, the epidermal growth factor receptor (EGFR) as a tumor-promoting factor can promote breast cancer cell proliferation and induce breast tumorigenesis." (PMID 36611922, 2022). "Furthermore, EGFR expression was associated with worse prognosis, specifically when co-expressed with HER2 in advanced breast cancer." (PMID 36432687, 2022).
breast carcinoma (continued). "The mono-methylation of epidermal growth factor receptor (EGFR) R1175 by the PRMT5-MEP50 complex in breast cancer favorably controlled its trans-autophosphorylation at Tyr 1173, resulting in endogenous SHP1 recruitment to attenuate son of sevenless (SOS) phosphorylation and ERK activation." (PMID 35493527, 2022). "That study showed EGFR overexpression in 35% of the 306 HER2+ breast cancer specimens." (PMID 36291900, 2022). "WT-161 also induced the apoptotic cell death of various breast cancer cells by decreasing the expression levels of epidermal growth factor receptor (EGFR), epidermal growth factor receptor 2 (HER2), and estrogen receptor α (ERα), as well as downstream signaling." (PMID 36076996, 2022). "We hypothesize that treating ER+ letrozole-resistant T47D breast cancer cells (T47DaromLR) with a combination of 10 μM glyceollin and 0.5 μM lapatinib (a dual EGFR/HER2 inhibitor) will decrease cell proliferation through induction of apoptosis." (PMID 35270029, 2022). "EGFR measurement is inexpensive and straightforward and can be measured in TN breast cancer." (PMID 36158981, 2022). "Nuclear EGFR induces resistance to anti-EGFR therapy and is a therapeutic target for breast cancer." (PMID 35745583, 2022). "We speculated that this disparate result may be caused by the additional activity of afatinib against Her2, which has been investigated in the context of breast cancer and other EGFR and Her2-driven cancers." (PMID 35720127, 2022). "EGFR expression is markedly higher in TNBC compared to other breast cancer subtypes." (PMID 35681787, 2022). "Interestingly, these effects were reversed once they blocked the actions of epidermal growth factor receptors (EGFR), suggesting that BPA’s association with breast cancer is dependent on STAT3 signaling." (PMID 35955412, 2022). "Chrysin was reported to inhibit EGFR in breast cancer stem cells." (PMID 36077069, 2022). "EGFR O-glycosylation in breast cancer was impacted by GALNT8." (PMID 36058918, 2022). "Consequently, this facilitates DNA hypermethylation at the promoter region of microRNA-200a (miRNA-200a), stimulating the expression of hepatocyte growth factor (HGF) and epidermal growth factor receptor (EGFR) and promoting breast cancer progression." (PMID 36672839, 2022). "CTNNB1 and EGFR are highly expressed in carcinomas such as lung and breast cancers." (PMID 36437827, 2022). "Furthermore, treatment with ErbB2- and EGFR-specific TKI lapatinib reduced P-PKM2 Tyr105 levels in a breast cancer mouse model." (PMID 35054968, 2022). "EGFR, as a member of the receptor tyrosine kinase family, is closely associated with the occurrence and development of NSCLC, ovarian cancer and breast cancer." (PMID 36401689, 2022). "Studies have shown that nucleic acid therapeutics can be transported to breast cancer tumors expressing EGFR (epidermal growth factor receptor) through extracellular vesicles and may have anti-metastatic effects." (PMID 35745835, 2022). "Previous research demonstrated that as hormone-dependent, letrozole-sensitive breast cancer cells transition to a hormone-independent and letrozole-resistant phenotype, they utilize growth factor signaling pathways such as EGFR, p38/MAPK, and HER2 as a mechanism of survival." (PMID 35270029, 2022). "Our study thus suggests the probable direction that could be further explored in inhibiting EGFR protein harboring breast cancer." (PMID 37654845, 2022). "The analysis represented the enriched pathways in cancer affected by ALT and Brv-A include EGFR-tyrosine kinase inhibitor, PI3k-Akt signaling pathway, RAS signaling pathway, RAP1 signaling pathway, IL-17 signaling pathway, and breast cancer pathway along with EGFR tyrosine kinase inhibitor." (PMID 35281907, 2022).
breast carcinoma (continued). "Despite this, mutations in CDC42-related genes are very low at between 0.1 and 1.7% and the elevated CDC42 expression in breast cancer is thought to be due to activation of oncogenes or cell surface receptors (for example; epidermal growth factor receptor (EGFR)) that lead to CDC42 upregulation." (PMID 35087170, 2022). "In addition, breast cancer cells possess overexpressed epidermal growth factor receptor (EGFR) on the membrane surface, which is involved in various processes promoting tumorigenesis and metastasis." (PMID 36015599, 2022). "Moreover, both in GC as well as in breast cancer, several preclinical models have shown a relationship between the upregulation or activation of the EGFR and HER3, with the resistance to HER2." (PMID 35267574, 2022). "Our novel compounds could target EGFR-related cancers and can reduce the severity of several cancers, including lung and breast cancer." (PMID 36457709, 2022). "The earliest studies exploring RAL-GTPases in breast cancer suggested that RALA may be involved in tamoxifen resistance in breast cancer cells and EGFR-independent growth." (PMID 35626682, 2022). "Both neratinib and lapatinib have shown activity in EGFR-amplified breast cancer cell lines." (PMID 35142964, 2022). "Among miRNAs potentially involved in the cross-talk between EGFR-stimulated MSCs and breast cancer cells, we identified miR-23c and suggested a role of this miRNA as a tumor suppressor in MDA-MB-468 and MDA-MB-231 breast cancer cells, through the inhibition of IL-6R." (PMID 35406622, 2022). "This combination could reduce the metastatic feature of breast cancer via regulating EGFR mediating signaling pathways." (PMID 35835840, 2022). "EGFR plays an important role in the progression and development of several cancers in humans, on an average 50–60% of lung adenocarcinoma, colon cancer, and breast carcinoma." (PMID 36457709, 2022). "Lapatinib (Tykerb), a dual tyrosine kinase inhibitor that interrupts the HER2/neu and epidermal growth factor receptor (EGFR) pathways, was approved for the use of breast cancer and other solid tumors, and was also shown to inhibit ABCB1- and ABCG2-mediated MDR in cancer cells." (PMID 35327403, 2022). "Moreover, ITGB4 transactivates EGFR/Her2 signaling and promotes lung metastasis in breast cancer cells." (PMID 34693476, 2022). "EGFR alone cannot drive the progression of metastatic PCa tumours, but its linked to its upstream fibrinolytic receptor ANXA2, are together known to the PCa and breast cancer progression." (PMID 36224238, 2022). "For example, exosomes modified with GE11 peptide could deliver let-7a miRNA into the epidermal growth factor receptor (EGFR)-overpressed breast cancer cells (HCC70, HCC 1954, and MCF-7)." (PMID 36313380, 2022). "Interestingly, knocking down GD3S in MDA-MB-468 mammary carcinoma cells induces increased sensitivity, in vitro and in vivo, of the EGFR inhibitor gefitinib." (PMID 35267607, 2022). "To clarify the exact RBP in nuclear EGFR-mediated cancer progression, we evaluated the clinical value of those RBPs in TNBC and found NONO was significantly upregulated in TNBC and closely associated with breast cancer malignancy." (PMID 35013116, 2022). "Furthermore, we demonstrated that the enzymatic conjugation of RBCEVs with EGFR‐targeting nanobodies facilitates specific uptake of RBCEVs by EGFR‐positive breast cancer cells in vitro." (PMID 35430766, 2022). "It is well known that the EGFR-sensitive mutation enhances the phosphorylation of MAPK and Akt in NSCLC, and our previous studies and others had documented that GPER1 can stimulate the phosphorylation of MAPK and Akt through activation of EGFR in breast cancer." (PMID 35664735, 2022). "Increased EGFR expression is frequently found in breast cancer including TNBC." (PMID 35992877, 2022). "Correlation of EGFR mutation and HER2 status of breast cancer." (PMID 36313724, 2022).
breast carcinoma (continued). "FEN1 was reported to elevate the expression of DNMT3A and promote their interaction among FEN1/PCNA/DNMT3A and suppressed the expression of miR-200a-5p, leading to upregulation of miR-200a-5p targets, MET and EGFR, which contribute to enhancement of growth of breast cancer cells." (PMID 35620052, 2022). "Starting from this evidence, we hypothesized that the EGFR was able to modulate in MSCs a set of miRNAs potentially involved in breast cancer progression." (PMID 35406622, 2022). "NK1R has been shown to modulate EGFR phosphorylation in breast cancer and glioblastoma cells." (PMID 35013118, 2022). "The detection of EGFR as a protein expressed in the serum of breast cancer patients may be a non-invasive practice with better prognostic stratification." (PMID 36158981, 2022). "The epidermal growth factor receptor (EGFR) belongs to the tyrosine kinase family that is overexpressed in various cancers, such as breast cancer, prostate cancer and colorectal cancer, and plays an important role in cancer proliferation, growth and angiogenesis." (PMID 36358960, 2022). "It was reported that bisecting N-GlcNAc modification on EGFR and small extracellular vesicles can diminish malignancy of breast cancer cells, which may contribute to the development of novel targets in breast cancer therapy." (PMID 35954297, 2022). "This suggests that overexpression of c-MYC in breast cancer can activate EGFR signalling." (PMID 35267559, 2022). "Because it acts on the EGFR signaling pathway, musarin may potentially be effective against other types of cancers, including lung and breast cancer." (PMID 36359361, 2022). "On average, 50–70% of lung, colon, and breast carcinoma express EGFR." (PMID 35409325, 2022). "Thus, activation of the EGFR leads to the increased downstream activity of caspases 8 and 9, which leads to apoptosis of breast cancer cells." (PMID 35252243, 2022). "EGFR (epidermal growth factor receptor) is overexpressed in a variety of human cancers (including squamous cell carcinoma of head and neck, colon cancer, and some breast cancers) and therefore is regarded as an ideal target for cancer therapy or imaging purposes." (PMID 35517713, 2022). "Notably, DPP9 prefers to regulate the cell behaviour through EGFR signalling which is a dominant signalling in the TNBC subtype of breast cancer, DPP9 tends to be a pivotal molecule in TNBC." (PMID 35685372, 2022). "In addition, it has been reported that PRKG2 inhibits EGF-induced MAPK/c-Jun N-terminal kinase (JNK) signal transduction in human breast cancer cells and also inhibits the activation of EGFR and HER2 in gastric cancer cells." (PMID 36338974, 2022). "In addition, several studies have shown that PTPN12 is linked to a favorable prognosis in TNBC patients by suppressing multiple oncogenic tyrosine kinases, including HER2 and EGFR, thereby dampening breast cancer cell survival, migration and EMT." (PMID 35957898, 2022). "A fourth generation poly-lysine dendritic nanocarrier (P4LDN)-based targeted chemotherapy for breast cancer is attempted by incorporating an epidermal growth factor receptor (EGFR)-specific short peptide E2 (ARSHVGYTGAR) and the drug methotrexate (MTX) into a nanocarrier system." (PMID 35160746, 2022). "In conclusion, our data demonstrated that the EGFR signaling regulates in MSCs a wide number of miRNAs that might be involved in breast cancer progression." (PMID 35406622, 2022). "Furthermore, melittin reacted more specifically to HER2- and EGFR-overexpressing breast cancer cells and showed greater toxicity than bee venom." (PMID 35878198, 2022). "Nuclear-localized epidermal growth factor receptor (EGFR) highly correlates with the malignant progression and may be a promising therapeutic target for breast cancer." (PMID 35013116, 2022). "However, the role of the EGFR in modulating in MSCs the expression of miRNAs potentially involved in the progression of breast cancer remains largely unexplored." (PMID 35406622, 2022).